RN7SL753P (RNA, 7SL, cytoplasmic 753, pseudogene)
Gene: Miscellaneous RNA gene on chromosome 2 (202,333,439 to 202,333,728, forward strand). Ensembl gene ENSG00000264275.
Homologues: Orthologues: chimpanzee Metazoa_SRP (99% identical). Paralogues in human: RN7SL1 (83% identical), RN7SL126P (83% identical), RN7SL2 (83% identical), RN7SL3 (82% identical), RN7SL45P (82% identical), RN7SL336P (81% identical), RN7SL322P (81% identical), RN7SL709P (81% identical), RN7SL122P (80% identical), RN7SL220P (80% identical), RN7SL493P (80% identical), RN7SL357P (80% identical), and 702 more.